TNF (tumor necrosis factor)
Diseases named in the same sentence as TNF in open-access papers (continued):
Sharing a sentence is not in itself a finding about the gene and the disease.
viral infection (continued). "Upon viral infection of the host, host immune cells produce mediators of antiviral innate immune and inflammatory responses such as interferon (IFN), chemokines, interleukins (IL) and tumor necrosis factor (TNF)." (PMID 39555085, 2024). "Recently, it has demonstrated that aged TNF KO mice exhibit resistance to lethal infection with SARS-CoV-2 N501Y P21 virus infection without affecting virus titers in the lung compared with aged WT mice." (PMID 39652608, 2024). "In other cell types, the process may well be a response to an inflammatory insult, as tumor necrosis factor-α can also initiate TNT formation, as can viral infection." (PMID 39273001, 2024). "This possibility is further corroborated by its chemokine-like role and pro-inflammatory properties that may be inhibited by cationic ribosomal proteins RPL9 in LPS + HMGB1-stimulated TNF-α expression in macrophage-like RAW264.7 cells or in viral infections." (PMID 39494346, 2024). "This downregulation, coupled with TPF’s inhibition of the NF-κB nuclear translocation induced by TNFα, suggests that much like DMF, TPF modulates innate immune responses, creating a more favorable environment for viral infection and oncolysis in the context of replicating oncolytic viruses." (PMID 38932212, 2024). "It was also demonstrated that while SOCS1−/− mice experienced higher levels of TNFα, IL-10, and IL-17 compared to wild-type mice, in the context of viral infections, SOCS1 overexpression could decrease the concentrations of virally induced TNFα." (PMID 39867889, 2024). "TNF-α, IL-6, and IL-1β play a critical role in various inflammatory diseases, while MCP-1 expression is correlated with the pathogenesis of certain diseases or viral infections." (PMID 38275672, 2024). "Excessive production of other proinflammatory cytokines such as IFN-γ, TNF, and IL-12 may also be involved in exacerbated inflammation leading to tissue damage and mortality of EHDV-8 infected mice, similarly to other viral diseases 70,71." (PMID 38904031, 2024). "Pathways upregulated by infection with the HSV-1 KOS strain play roles in the regulation of immune response, tumor necrosis factor-alpha (TNF-α) production, response to viral infection and cell-fate commitment, which are all in the context of cell differentiation." (PMID 37569367, 2023). "In fact, treatment of patients with CHIKV with TNF-α antagonists, etanercept and adalimumab, showed promise with good tolerance without the reappearance of the viral infections manifestations." (PMID 37014125, 2023). "After viral infection, the body protects cells from viral infection by regulating the expression of cytokines, such as interferon, interleukin, and tumor necrosis factor, through nonspecific immunity." (PMID 36830548, 2023). "In terms of viral diseases such as hepatitis C virus (HCV) infections, anti-TNF-α agents used to prevent overreactive TNF-α-related biological activities are proven safe and beneficial in delaying HCV reactivation that may lead to fatal liver failure." (PMID 37047115, 2023). "The cytokine analysis results showed that a PRV infection could increase the levels of TNF-α, IFN-γ and IL-6 and reduce the level of IL-4 to regulate the body’s immune response to a virus infection." (PMID 37508153, 2023). "Together, these results suggest that inhibition of SUMOylation may provide resistance against viral infections inducing IFN1, and protection against polymicrobial peritonitis by inducing early TNFα production." (PMID 37520526, 2023). "In addition, pathways related to bacterial/viral infection and immune responses were among the top pathways altered by EPS, including interferon and TNF signaling." (PMID 38074643, 2023). "After a viral infection, the body regulates the expression of cytokines such as interferons, tumor necrosis factor and interleukins through nonspecific immunity to protect cells from the viral infection." (PMID 37508153, 2023).
viral infection (continued). "Tumor necrosis factor (TNF) is a proinflammatory cytokine that is produced in response to a large variety of stressors, including viral infection and injury, and it can initiate repair processes by inducing the expression of proinflammatory genes or by triggering cell death." (PMID 37494451, 2023). "We should keep in mind that the SARS-CoV2 virus infection - similar to other viral diseases, influenza, etc. is, in fact, related to clinical manifestations such as lack of appetite that suggests an involvement of tumor necrosis factor (TNF)." (PMID 37520878, 2023). "The correct ratios of immune subsets are known to be critical during viral infections, such as the CD4/CD8 ratio in HIV-infection, or the total CD4+ and CD8+ T-cells producing IFN-γ or TNF-α as predictors of the immune response after vaccination against tuberculosis and herpes zoster." (PMID 36875099, 2023). "Notably, it was shown that the induction of the synthesis of cytokines, TNFα, IFNβ and IL6 in macrophages by viral infection was RKIP dependent." (PMID 35892864, 2022). "Likewise, poliovirus protein 3A inhibits the transport from the endoplasmic reticulum to the Golgi apparatus, blocks TNF-induced apoptosis and even limits IL-6, IL-8 and IFN-β secretion during viral infections." (PMID 35222374, 2022). "Δ382 SARS-CoV-2 infected patients had higher CD4+ and CD8+ T cells expressing TNF-α than WT infected patients following peptide stimulation, indicating a more robust SARS-CoV-2 specific T cell response in patients with mutant virus infection." (PMID 34716845, 2022). "The upregulation of Gal-3BP during viral infection has been demonstrated to be mediated by different cytokines that are commonly induced by virus infection, such as interferons (i.e., IFN-α, IFN-β, and IFN-γ), tumor necrosis factor alpha (TNF-α), and by double-stranded polynucleotides." (PMID 35806317, 2022). "Viral infection by SARS-CoV-2 initially activates innate immune cells, thus recruiting them to the sites of infection and producing pro-inflammatory cytokines including IL-6, IL-12, and TNF-α, etc." (PMID 35330839, 2022). "Galectin-3 expression is known to be induced in viral infections and by a multitude of molecules that either mimic or are characteristic of ongoing inflammation and microbial infection, such as IFN-α, IFN-β, IFN-γ, TNF-α, poly(I:C), dsRNA, and dsDNA." (PMID 36131342, 2022). "After DAE treatment, the production of IFN-γ and TNF-α was higher than that in the infected control, especially IFN-γ, suggesting that DAE might inhibit viral infection in the early stage of PRV infection by enhancing the inflammatory response." (PMID 36699332, 2022). "In addition, the expression of four immune-related genes, TRAF3, IL-1β, TNF-α, and TLR2, was differentially altered following viral infection." (PMID 36552207, 2022). "In comparison with the ASFV-WT-infected PAMs, the majority of the dysregulated mRNAs during ASFV-ΔH240R infection were involved in innate immunity signaling (including TNF, MAPK, and JAK-STAT signaling pathways), receptor signaling, metabolic networks, and other pathways involved in viral infection." (PMID 34787458, 2022). "Other cytokines and chemokines, including CXCL-8 (IL-8), CXCL-10 (IP-10), TGF-β and TNF-α protein, and type I IFN (IFN-β) and type III IFN (IFN-λ1) mRNA were increased to a similar extent during viral infection and co-infections with either of the PA isolates and HRV16." (PMID 35265536, 2022). "Besides, virus-induced secretion of cytokines, such as tumor necrosis factor α (TNF-α), types I and II interferon (IFN), and interleukin (IL)-4/8/10, are evidenced to participate in the process of virus infection." (PMID 34869732, 2021). "High levels of several proinflammatory mediators (e.g., interleukin-1β [IL-1β], IL-6, tumor necrosis factor α [TNFα], and CXCL8) are detected early after viral infection, and the resolution of this inflammatory response seems impaired in patients with severe disease progression." (PMID 34548411, 2021).
viral infection (continued). "Without viral infection treatment of cells with the inflammatory cytokines, Tumor Necrosis Factor (TNF)-α or type I interferon has the same effect." (PMID 34199077, 2021). "Second, the ability of A179L to enhance TNF-α and virus-induced necroptosis has not been verified in a virus infection setting." (PMID 34960759, 2021). "The TNF-α levels increased after exposure to LPS, the rise being largely independent of the viral infection, albeit a small but insignificant increase was observed in M-MΦ after RV infection." (PMID 34975859, 2021). "As previously reported, IRF1 could be induced by many cytokines such as IFNs (-α, -β, -γ), TNF-α, IL-1, IL-6, LIF and virus infection mediated by STAT and NF-κB." (PMID 34930359, 2021). "It has been documented that TLRs could activate ADAM17 leading to tumor necrosis factor alpha (TNF-α), interleukin-6 (IL-6) and epidermal growth factor receptor (EGFR) after viral infection." (PMID 33926110, 2021). "Thus, Th1 cells are activated after a viral infection or tumor cells and produce interferon-γ (IFN-γ) and tumor necrosis factor (TNF), to recruit CD8 + cytotoxic T cells (CTLs) for an antiviral or antitumor response." (PMID 34575531, 2021). "In addition, several pathways, like IL-17, AGE-RAGE, TNF, HIF-1, PI3K-AKT, NOD-like receptor, T/B cell receptor, and virus infection-related pathways, exerted vital parts in FXF in the treatment of pulmonary fibrosis." (PMID 34394391, 2021). "Viral infections during pregnancy elicit high levels of circulating IFN-γ, TNF-α, IL-6, and TGF-β." (PMID 33430059, 2021). "We only observed a TNF-induced change in cellular decision strategy during viral infection and not in response to other stresses such as bacterial lipopolysaccharide or DNA damage." (PMID 34016976, 2021). "These core targets were mostly concentrated on several KEGG pathways, like IL-17, AGE-RAGE, TNF, HIF-1, PI3K-AKT, NOD-like receptor, T/B cell receptor, and virus infection-related pathways, indicating their important parts in the treatment of pulmonary fibrosis." (PMID 34394391, 2021). "Notably, TNF signaling, NF-κB signaling, HIF-1 signaling, metabolism, and immune pathways were upregulated upon the virus infection." (PMID 34408131, 2021). "On the other hand, E7 inhibits cytostatic cascade of certain cytokines (transforming growth factor β (TGF-β), tumor necrosis factor α (TNF-α), IFN-α, IFN-γ, and insulin-like growth factors (IGFs)) involved in regulating cellular growth and immune reaction to viral infection." (PMID 34833157, 2021). "Since viruses stimulate macrophage interferon-alpha synthesis, which inhibit tumor necrosis factor (promoter of PCT release), PCT rates may be lowered in viral infections." (PMID 34221509, 2021). "Whereas the downregulation of lncRNA PVT1 seems to protect pancreatic β cells from injury, both up-regulated MALAT1 and NEAT1 had been related to inflammatory mediators (TNF-alpha, IL-6, CXCL10), SLE pathogenesis and innate immune response against viral infections." (PMID 35058920, 2021). "With H1N1 infection, human macrophages and neutrophils produced significantly higher levels of pro-inflammatory cytokines and chemokines, such as TNF-α, IL-1β, IL-6, and fractalkine, compared to that with no virus infection." (PMID 32901688, 2020). "Viral infection facilitates the recruitment of accessory cells and T cells to the islets leading to site directed production of inflammatory cytokines, particularly INF-α, INF-β, IFN-γ, tumor necrosis factor (TNF) and IL-1β." (PMID 33679609, 2020). "Following chronic LCMV infection, upregulation of inhibitory molecules such as PD-1, Lag3, Tim3 and loss of effector functions such as interferon gamma (IFN-y) and tumor necrosis factor (TNF) production occurs, impeding the CD8 T cell-mediated control of viral infection." (PMID 32547546, 2020).
viral infection (continued). "BBB permeability could increase in response to proinflammatory stimuli such as tumor necrosis factor-α (TNF-α), interleukin-6 (IL-6), and IFN-γ, enabling infiltration of immune effectors into the CNS to clear viral infection." (PMID 32268591, 2020). "Along with direct antiviral activity, TCMs could be beneficial in preventing viral infection due to its immune-modulatory effect, producing of IFN- and TNF-." (PMID 30911327, 2019). "In addition to allowing efficient BV transduction, wtBV has been shown to immunostimulate the release of inflammatory cytokines, including INFs, TNF-α, IL1A, IL1B and IL6 in mammalian cells and confer protection from lethal virus infection in mice." (PMID 31649751, 2019). "Previously, reported data suggest that acquisition of resistance to TNF and TRAIL is an early event during viral infection and may be required for viral persistence as well as for malignant progression." (PMID 30625987, 2019). "PCLS isolated from non-sensitized mice showed a strong antiviral response to active viral infection, which resulted in enhanced secretion of IFN-α (0.4 vs. 112 pg/mg), IFN-β (31 vs. 779 pg/mg), IFN-γ (7 vs. 25 pg/mg), MCP-1 (73 vs. 313 ng/mg), TNF-α (2.5 vs. 3.2 ng/mg), and IP-10 (9 vs. 60 ng/mg)." (PMID 31640701, 2019). "Furthermore, examination of IFN and ISGs mRNA transcripts in cells infected with FMDV S fragment mutant demonstrated an upregulation of Mx-1, IFNβ, IL-6, TNFα, and IRF7 when compared to WT virus infection." (PMID 30483224, 2018). "We found that patients with viral infections showed higher levels of TNF-α, IL-6, and MCP-1 than those without." (PMID 28352642, 2017). "The miR-US5-1/miR-UL112-3p mutant virus infection resulted in increased secretion of IL-6, CCL5, and TNF-α (in THP-1 cells) compared to WT-infected cells, which was significantly reduced in cells infected with the miRNA mutant virus expressing shRNAs targeting IKKα and IKKβ." (PMID 28270578, 2017). "MYXV is able to successfully replicate in some cultured human cells, such as human primary fibroblasts, as long as the infected cells do not induce IFN and/or TNF as a consequence of the virus infection." (PMID 28157174, 2017). "At day 2 postinfection, both TNF-α and IL-6 transcripts were moderately induced by wild-type virus, while CCL2, CCL4, CXCL9, and CXCL10 mRNA levels were all highly elevated by wild-type virus infection." (PMID 29138302, 2017). "Thus, here we provide evidence that following viral infection, IL-33 is produced in the CNS to counteract the deleterious effects of pro-inflammatory cytokines IFN-γ and TNF-α, as well to shift macrophage response to a M2-protective phenotype." (PMID 27334012, 2016). "It is not surprising that due to the key role of TNFα in the host protection to viral infections, some viruses have developed different ways to interfere with the TNFα pathway." (PMID 27351838, 2016). "The mechanism explaining how TNFα facilitates viral infection and its deleterious effects in the host has not yet been proposed." (PMID 27351838, 2016). "Furthermore, the capacity of M-Tha to interact with RelAp43 was shown to be crucial for the control of the expression of four genes (IFN, TNF, IL8 and CXCL2) during viral infection." (PMID 28000711, 2016). "The TNF pathway acts in mammalian response to bacterial and viral infections functions without the involvement of PGRPs." (PMID 25674081, 2015). "The ability of IFNγ, but not TNFα, to inhibit virus infection was also demonstrated in human macrophages." (PMID 26562011, 2015). "The lack of PCT response to viral disease seems to be due to stimulation of macrophages to release interferon, which inhibits tumor necrosis factor (TNF) synthesis that, in turn, is necessary for tissues to synthesize PCT." (PMID 25073709, 2014).
viral infection (continued). "Generic activation of the NF-κB response by inflammatory mediators such as TNF-α also did not elicit the reorganization of IKKβ further underscoring the idea that this was a specific virus infection dependent event." (PMID 24586253, 2014). "As a major transcription factor for antiviral and immune stimulatory activities, NF-κB is thought to play an important role in the induction of pro-inflammatory molecules, such as interleukin-1β (IL-1β), and tumor necrosis factor α (TNF-α), upon cellular responses against a virus infection." (PMID 25699183, 2014). "Interestingly, SeV- or HSV-1-induced expression of the proinflammatory cytokines TNFα and IL-6 was inhibited by RNF26 knockdown at all examined time points after viral infection." (PMID 25254379, 2014). "Once activated, NK cells work to control viral infections by secreting IFN-γ and TNF-α." (PMID 24520300, 2014). "Safety and efficacy of anti-TNF agents in chronic hepatitis B are not known, and data available on reactivation of these viral infections are conflicting." (PMID 23606869, 2013). "Coherently, we found that viral infection induces the accumulation of an active form of CTNNB1 and that CTNNB1 gene silencing increases SeV-induced IFNB1, IFIT1 and TNF expression, as well as NFKBIA (IκBα) phosphorylation at serine 32 (P-Ser32) to release NF-κB inhibition." (PMID 23785285, 2013). "DHA pretreatment also significantly reduced IL-6 and TNF-α pro-inflammatory cytokine production during both TLR-3 and TLR-7 microglia activation, proving that DHA can exert its anti-inflammatory properties in both types of simulated viral infections." (PMID 23398903, 2013). "In addition, in peripheral macrophages, miR-155 is strongly induced upon several TLR ligands, as well as bacterial or viral infection, oxidized LDL, TNF-α, and interferon-γ." (PMID 24244499, 2013). "As indicated in the results, the production of IFN-α, IFN-β, IL-1β, IL-6 and TNF-α of PAMs is improved highly after CSFV Shimen strain infection, supposing the cells might use this way to defense the virus infection and to protect the host from harm." (PMID 24034559, 2013). "CD8 T cells control viral infection via several mechanisms including direct cytotoxicity using perforin, granzyme, TRAIL or Fas-FasL interactions, or through the secretion of antiviral cytokines such as tumor necrosis factor (TNF) and gamma interferon (IFNγ)." (PMID 24153060, 2013). "All the patients, at the beginning of anti-TNF treatment, exhibited normal liver function and a negative viral load (<200 IU/mL) due to a resolved viral disease." (PMID 23606869, 2013). "BMDCs produce pro-inflammatory cytokines including TNFα and IL6 upon viral infection." (PMID 23936008, 2013). "Further, similar to the effects of dsRNA, infecting BSMCs with RV1B resulted in dose-dependent expression of CXCL8 mRNA whereas TNF-α expression was not appreciably affected after 24 h viral infection." (PMID 23658644, 2013). "The secretion of TNF-α protein from the amnion cells was not changed after the virus infection, and the TNF-α protein produced by the amnion cells had no biological activity." (PMID 22899878, 2012). "LPS was used as a positive control to trigger TNFα production independent of viral infection showing that all cells were competent for TNFα production." (PMID 22952450, 2012). "In summary, these data indicate a highly specific response of macrophages through a coordinated negative regulation of multiple sterol pathway members upon viral infection or treatment with IFNγ or β but not IL1β, TNF, or IL6." (PMID 21408089, 2011). "When tested for induction of an NF-κB controlled cytokine such as TNF, this cytokine level was also significantly increased within one hour, specifically in case of vMyxM013-KO virus infection but not WT-MYXV." (PMID 19851467, 2009).